CXCL10 (C-X-C motif chemokine ligand 10)
Diseases named in the same sentence as CXCL10 in open-access papers (continued):
Sharing a sentence is not in itself a finding about the gene and the disease.
myeloma (19 papers, 2014 to 2025). "Current risk stratification models for MGUS/Smoldering Multiple Myeloma (SMM) increasingly incorporate inflammatory and metabolic biomarkers, with our findings supporting CXCL10 and IL‐6 as potential candidates for dynamic monitoring." (PMID 41498034, 2025). "High concentrations of CXCL9 and CXCL10 interfere with the infiltration of natural killer (NK) cells into the MM microenvironment and limit their anti-myeloma activity." (PMID 36733370, 2022). "More recently, CXCL10-Ig was used to treat myeloma and it performed well in triggering immune systems to defend tumor cells and significantly decreasing tumor growth." (PMID 36612163, 2022). "CXCL10 activates CXCR3A receptors on myeloma cells, which attenuated apoptosis mediated by FAS (CD95)." (PMID 28176846, 2017). "Giuliani23 showed that CXCL10 can affect the biological characters of myeloma through autocrine modes of action." (PMID 28176846, 2017). "Another possible mechanism for the pro-tumorigenic effects of heparanase in myeloma was recently elucidated in animal models, which revealed that heparanase enhances myeloma progression via CXCL10 downregulation." (PMID 25105093, 2014). "For example, CXCL10 was found to stimulate anti-tumor immunity and thereby suppress myeloma." (PMID 36612163, 2022). "A role for CXCL10 in the control of myeloma cell growth has indeed been observed." (PMID 28389623, 2017). "In addition they also observed increased levels of CXCL10 within the bone marrow of patients with multiple myeloma and this was correlated with a decrease in the number of CXCR3+ NK cells within blood." (PMID 28389623, 2017). "Very recently, we showed that indeed administration of CXCL10-Ig in a clinical set-up of myeloma that CXCL10-Ig could be used for immunotherapy of this disease, and that aside from enhancing antitumor immunity, it directly suppresses tumor growth." (PMID 26648938, 2015). "Moreover, activated tumour-specific T cells that express CXCR3 were shown to infiltrate CXCL10-expressing myeloma cells more efficiently than non-CXCL10-expressing myeloma cells." (PMID 26115406, 2015). "Along with this, a single chemokine named CXCL10 could be used to induce antitumor immunity, and thereby suppress myeloma." (PMID 26648938, 2015). "The peculiar multiple myeloma microenvironment, characterized by up-regulated levels of several inflammatory chemokines, including the CXCR3 receptor ligands CXCL9 and CXCL10, limits NK cell positioning into the bone marrow by interfering with CXCR4 function." (PMID 31699153, 2019). "Interestingly, the expression of both CXCL9 and CXCL10 was markedly increased in the bone marrow of the patient groups, and appeared to increase in a progressive fashion during the clinical transition from MGUS to myeloma although a definitive longitudinal study would be needed to confirm this." (PMID 28389623, 2017).
parasitemia (19 papers, 2009 to 2025). "There was a trend towards a decrease in temperature and the levels of the top five most upregulated cytokines during the participant’s second exposure to high parasitemia, IL-10, CXCL10, IL-1RA, IFNγ, IL-6." (PMID 38890271, 2024). "IP-10/CXCL10 has been detected in various body fluids in bacterial, viral, fungal, and parasitic infections." (PMID 30379898, 2018). "We also investigated whether the increase in parasitemia, due to the presence of CXCL10, is a result of an increase in the number of daughter cells per schizont-infected cell." (PMID 34381047, 2021). "Furthermore, CXCL10 has been considered a novel biomarker for severity of parasitic diseases." (PMID 32393333, 2020). "We assessed the serum levels of six cytokines (i.e. IL-1α, IL-1β, IFNγ, CXCL10, CXCL9, TNFα) at the first peak of parasitemia of both 1/148 and IL3000 infections." (PMID 35787830, 2022). "Serum levels of IL-6, IL-27, CCL3, CCL5, CXCL10, CCL11, and CCL17 in patients with different parasitic infection profiles living in the rural community of Brejo do Amparo, Januária, Minas Gerais, Brazil." (PMID 33777015, 2021). "P.berghei parasitemias was observed in both wild type (WT) and CXCL10−/− mice although below 15% in CXCL10−/− mice." (PMID 22479586, 2012). "Besides clearing parasitemia, this treatment also resulted in a lower pulmonary mRNA expression of the inflammatory chemokines CCL2 and CXCL10, and of the cytokines tumor necrosis factor-α (TNF-α), IFN-γ, and IL-10." (PMID 33664739, 2020). "Higher levels of some pro-inflammatory mediators such as IL-6, MCP-1/CCL2 and IP-10/CXCL10 were observed in P. vivax-infected patients, which were re-established after anti-malarial treatment, suggesting that the parasite infection triggered an inflammatory response." (PMID 28118834, 2017). "Remarkably, we observed the highest parasitemia levels using FACS counting (by ~3-fold) validated by Giemsa smear counting in the three conditions in which the parasites were exposed to CXCL10 as compared to conditions in which CXCL10 was absent but other chemokines were present." (PMID 34381047, 2021). "Serum concentration of IL-1α, IL-1β, IFNγ, CXCL10, CXCL9, TNFα in non-infected mice and mice infected with either 1/148 or IL3000, at the first peak of parasitemia (Mean ± SEM; N=3–4)." (PMID 35787830, 2022).
preeclampsia (19 papers, 2010 to 2025). Preeclampsia is a hypertensive disorder of pregnancy that is characterized by new-onset hypertension with proteinuria presenting after 20 weeks of gestation, and depending on mild or severe forms may initially present with severe headache, visual disturbances, and hyperreflexia. "Specific periodontal pathogens activate TLRs, intensifying placental inflammation that upregulates sICAM-1, sVCAM-1, MCP-1, IL-17, MMPs and CXCL10 implicated in preeclampsia." (PMID 41394354, 2025). "Elevated CXCL10 cause placental inflammation and are associated with preeclampsia." (PMID 41394354, 2025). "Our multiplex immunoassays confirmed previous reports in preeclampsia of increases in plasma cytokines, including angiostatic CXCL10 and CXCL12/SDF-1α." (PMID 35455936, 2022). "We therefore additionally monitored the expression of two key mediators in the placenta from these mice: CXCL10 (originally IP-10) and CXCL12 (originally SDF-1) are both implicated in preeclampsia and in the innate immune response to Toxoplasma gondii." (PMID 30691477, 2019). "CXCL10 is a key mediator in preeclampsia and in the innate immune response to Toxoplasma Gondii, two of the best established immune risk factors for schizophrenia, so this has implications for understanding gene × environment risk interactions in the disease." (PMID 30691477, 2019). "Women with preeclampsia show increased circulating levels of CXCL10, CXCL11, CXCL12, and CXCL3." (PMID 41463301, 2025). "Furthermore, patients with preeclampsia had significantly higher serum concentrations of CXCL10/IP-10 compared to women with normal pregnancies." (PMID 39290698, 2024). "All proteins selected by PLSKO have been reported to be related to preeclampsia, including SERPINE1, HSPB1, CXCL10, DKK1." (PMID 40880285, 2025). "Numerous studies have demonstrated that patients with severe preeclampsia exhibit elevated plasma levels of various chemokines—CXCL8 (IL-8), CCL2 (MCP-1), CXCL10 (IP10), and CXCL12 (SDF-1)—compared to healthy pregnant women." (PMID 41463301, 2025). "This is consistent with our microarray results showing for instance an increased expression of Cxcl10, which similarly to PF4 exerts a potent pro-inflammatory and anti-angiogenic action that has been involved in the pathophysiology of preeclampsia." (PMID 23056436, 2012). "IP-10 (CXCL10) has pro-inflammatory and anti-angiogenic properties, and this chemokine has been proposed to be a potential link between inflammation and anti-angiogenesis in preeclampsia." (PMID 21906313, 2011). "Indeed, IP-10 (CXCL10) has pro-inflammatory and anti-angiogenic properties, and this chemokine has been proposed to be a potential link between inflammation and anti-angiogenesis in preeclampsia." (PMID 21126355, 2010). "The increase of CXCL10 at the maternal fetal interface is not specific for PTB and higher levels were detected in cases of preeclampsia, chorioamnionitis and villous inflammation." (PMID 37770883, 2023).
myocardial infarction (18 papers, 2011 to 2023). Gross necrosis of the myocardium, as a result of interruption of the blood supply to the area, as in coronary thrombosis. "As compared to WT relatives, myocardial infarction induction in Sting-deficient mice leads to decreased Ifnb1 expression and a strong drop in Cxcl10, Irf7, and Ifit1 expressions." (PMID 34659260, 2021). "The investigators of the Tromsø Study found that higher CXCL10 levels were protective for women when assessing the 10-year risk of incident myocardial infarction." (PMID 30210493, 2018). "In rats, Cxcl9 and Cxcl10 showed elevated expression in both remote and near infarcted regions of the heart and remained high up to 16 weeks after myocardial infarction." (PMID 35794867, 2022). "Regarding cardiovascular disease, cGAS critically mediates inflammation post-myocardial infarction (MI), and induces CXCL10, iNOS expression and M1 differentiation." (PMID 33552072, 2020). "CXCL10 was also elevated in acute myocardial infarction, measured 3–5 days after admission." (PMID 30210493, 2018). "In contrast, Cxcl10–/– mice subjected to myocardial infarction were characterized by enhanced adverse ventricular remodeling, early expansion of the fibrotic scar, and increased neutrophil infiltration with marked reduction of recruitment of CXCR3 expressing leukocytes and T cells." (PMID 30210493, 2018). "CXCL10, also known as interferon-inducible protein-10 (IP-10), a member of chemokine family, was one of the down-regulated platelet proteins in dogs with acute CHF in the present study, similar to the results of serum CXCL10 in mice with myocardial infarction." (PMID 33256720, 2020). "Furthermore, the antifibrotic properties of CXCL10 after myocardial infarction and inhibition of cardiac fibroblast migration manifest in a CXCR3-independent manner and are probably rooted at the level of CXCL10-GAG interactions." (PMID 29379506, 2017).
uveitis (18 papers, 2012 to 2025). An inflammatory process affecting a part of or the entire uvea. "CXCL10 levels have also been found to be increased in ocular fluids from patients with uveitis, suggesting these interactions parallel those in human disease." (PMID 39198470, 2024). "As for the genes in the non-lymphoid cells, both Cxcl2 (rescued in monocytes and neutrophils) and Cxcl10 (rescued only in monocytes) possibly contributed to the progression of uveitis by recruiting T cells and DCs." (PMID 34484247, 2021). "Third, given several differences of cytokine/chemokine transcript regulation (e.g. of Cxcl1 and Cxcl10) using RT-qPCR, it would be of interest to confirm these findings at the protein level, as well as future mechanistic studies to explore Nlrp12-mediated protection against uveitis." (PMID 35313917, 2022). "This study identified six significantly upregulated genes (CDKN1A, VCAM1, NFKBIA, ICAM1, IRF1, and CXCL10) and demonstrated that QHRGF exerts therapeutic effects on uveitis using in vivo experiments." (PMID 40718791, 2025). "IL-6, TNFα, and CXCL10 were found to be significantly elevated in the aqueous humor (AH) of patients with BD uveitis, sarcoidosis, and toxoplasmosis uveitis as compared to non-inflammatory controls." (PMID 37297843, 2023). "Secondly, adjunctive analysis of the CXCL13, CXCL10 and CXCL8 levels in the AH of patients with uveitis can be of value in the diagnosis and treatment of uveitis, either as part of a routine workup and assessment of the response to treatment or to confirm or refute a diagnosis of ocular syphilis." (PMID 38983560, 2022). "In conclusion, our study showed that uveitis associated with TB featured increased aqueous levels of IL-6, CXCL2, CXCL8, CXCL9, and CXCL10, which is not typical of an active ocular TB infection." (PMID 22509092, 2012). "However, CXCL10 levels were not significantly different in patients with enteritis, folliculitis or uveitis compared to patients without (p = 0.651, p = 0.557 and p = 0.066, respectively)." (PMID 29116188, 2017).
ulcerative colitis (17 papers, 2012 to 2025). An inflammatory bowel disease involving the mucosal surface of the large intestine and rectum. "IL-16 and IL-18 had a suggestive association with an increased risk of ulcerative colitis (UC), and CXCL10 had a suggestive association with an increased risk of Crohn’s disease (CD)." (PMID 37228614, 2023). "However, ALPK2, over-expressed in human IBD and mostly in ulcerative colitis, was equally expressed in Maffl/flCd4Cre and double-deficient Prdm1fl/fMaffl/fCd4Cre mice, while CXCL10 was increased in both ulcerative colitis and Crohn’s disease, and was highest in the double-deficient LPLs." (PMID 38609547, 2024). "The expression of the three ligands of CXCR3 (CXCL9, CXCL10, and CXCL11) is significantly increased in various diseases such as interstitial cystitis, ulcerative colitis, and myositis, and previous studies found that blocking CXCL10 can reduce the degree of the damage of these diseases." (PMID 35036436, 2022). "The three CXCR3 ligands (CXCL9, CXCL10 and CXCL11) are known to be differentially elevated under many conditions, such as interstitial cystitis, ulcerative colitis, and myositis; moreover, blocking CXCL10 may ameliorate the severity of these diseases." (PMID 28046003, 2017). "Interferon-γ-inducible protein-10 (IP-10 or CXCL10), which has been shown to play a role in inflammatory cell migration to the gut in ulcerative colitis (UC), was significantly increased in the PALA-treated group." (PMID 37475852, 2023).
experimental autoimmune encephalomyelitis (16 papers, 2014 to 2024). An autoimmune demyelinating disease of the central nervous system that is produced experimentally in animals by the injection of homogenized brain or spinal cord in Freund's adjuvant. "An increase in mRNA encoding CXCL10 in experimental autoimmune encephalomyelitis (EAE)-affected mouse brains under an inflammatory state was related to an increase in GFAP expression and astrogliosis." (PMID 35892669, 2022). "CXCL10 and CCL2 play a role in attracting T cells and monocytes, respectively, and have been strongly implicated in disease in experimental autoimmune encephalomyelitis (EAE), an animal for MS." (PMID 31636637, 2019). "For example, IL-1β induces CXCL-10 in astrocytes in culture, but it is also expressed by macrophages and has been shown to exacerbate experimental autoimmune encephalomyelitis." (PMID 25323767, 2014). "Indeed, CXCL10 mRNA is significantly increased during peak disease and reduced during recovery phases in the experimental autoimmune encephalomyelitis (EAE) model." (PMID 39333683, 2024). "Moreover, the upregulation of Ccl2, Ccl3, Ccl4, Ccl7, Cxcl9, and Cxcl10 is also related to the acute phase of experimental autoimmune encephalomyelitis." (PMID 35911717, 2022). "Likewise, microglia activation also begins early in disease development as RNAseq demonstrated that Mpeg1, a macrophage marker expressed also in microglia, was DE in 1-month Mcoln1−/− mice, as was Cxcl10, whose levels are also altered in models of experimental autoimmune encephalomyelitis." (PMID 33478506, 2021). "For instance, C-X-C motif chemokine receptor 3 (CXCR3) plays an important role in T cell recruitment to the CNS by binding with C-X-C Motif Chemokine Ligand 10 (CXCL10), CXCL9, and CXCL11 in experimental autoimmune encephalomyelitis (EAE)." (PMID 35674826, 2022). "Lif KO animals have increased expression of CXCL1, GM-CSF, RANTES/CCL5 and MIP-1β/CCL3 early during an experimental autoimmune encephalomyelitis model and reduced CCL2, CCL3, and CXCL10 at a later stage of the disease." (PMID 25277705, 2014). "CXCL10/IP-10, CCL2/MCP-1, CCL3/MIP-1a, CCL4/MIP-1b, CCL5/Rantes, CCL7/MCP-3 and CXCL9/Mig are among the described proinflammatory chemokines produced by immune cells and CNS glia in MS and in the animal model of MS, experimental autoimmune encephalomyelitis (EAE)." (PMID 26039252, 2015).
Allergy (15 papers, 2008 to 2024). An allergy is an immune response or reaction to substances that are usually not harmful. "We chose to assay CXCL-10 due to its important role as a key chemokine for the recruitment of Th1 lymphocytes into tissue and also because of the association of CXCL-10 with inflammatory and allergic diseases." (PMID 25253920, 2014). "Previously, in allergic reactions, increased mRNA expression of different proteins, namely, the chemokine interferon-γ-inducible protein-10 (CXCL10) and the related CXC chemokine receptor 3-activating chemokines (CXCR3) macrophage migration inhibitory factor (MIF) and IP-9, was identified." (PMID 39062959, 2024). "Therefore, Ccl7 and Cxcl10 are potential targets to overcome allergic diseases." (PMID 34093515, 2021).
breast tumor (15 papers, 2012 to 2026). "Supporting this observation, it was shown that DNA repair-deficient breast tumors were associated with CD4+ and CD8+ lymphocyte infiltration and that cells from these DNA repair-deficient breast tumors expressed the chemokines CXCL10 and CCL5 more strongly." (PMID 37420037, 2023). "This appears to be the case in the present studies where IOA-289 decreased the plasma concentrations of CCL2, CXCL9, and CXCL10, together with its effect of inhibiting the growth of E0771 breast tumors." (PMID 37296899, 2023). "The secreted CXCL9 and CXCL10 bind to CXCR3 on the surface of a subpopulation of breast tumour cells, which promotes initiation and growth of metastatic tumour cells." (PMID 35869057, 2022). "Our findings provide a mechanistic link between the COX pathway and CXCL9/CXCL10 chemokine secretion into the tumor microenvironment of human breast tumors." (PMID 22333315, 2012). "Moreover, in breast tumours, MSCs can secrete the chemokine CXCL10 and chemokine (C–C motif) ligand 5 to regulate tumour cells." (PMID 35869057, 2022). "A recent study also showed that overexpression of TILRR in BT474, a human breast tumor cell line, significantly potentiates the expression of immune and inflammation-associated genes, including IL-6, IL-8/CXCL8, IP-10 (interferon gamma-induced protein 10)/CXCL10, MCP-1/CCL2, and RANTES/CCL5." (PMID 34360591, 2021). "Moreover, secretion of CXCL10 was increased in supernatants of 4T1 breast tumor cells in which nuclear IP3 was buffered, but it was unaffected in ΔIP3-NLS infected cells (control = 1.3 ± 0.2 pg/mL; ΔIP3-NLS = 1.7 ± 0.2 pg/mL; IP3-sponge-NLS = 5.4 ± 0.6 pg/mL." (PMID 28376104, 2017). "More specifically, our study demonstrates that aged human and mouse breast tumor cells produce lower levels of the T cell–attracting chemokines CXCL9 and CXCL10." (PMID 41332581, 2025). "To approach our hypothesis that the COX system will have a significant impact on the CXCR3 ligand milieu of breast tumor environment we first investigated the effect of exogenous PGE2 on CXCL9 and CXCL10 release." (PMID 22333315, 2012).